MIR4713HG (MIR4713 host gene)
Synonyms: RP11-108K3.1
Gene: Long non-coding RNA gene on chromosome 15 (51,037,174 to 51,322,480, forward strand). Ensembl gene ENSG00000259240.
Diseases named in the same sentence as MIR4713HG in open-access papers:
MIR4713HG is named in the same sentence as 1 disease in open-access papers, as found by Europe PMC text mining. Sharing a sentence is not in itself a finding about the gene and the disease.
MIR4713HG shares sentences with these, for which no sentence is quoted: colorectal cancer (1 paper).